CXCL1 (C-X-C motif chemokine ligand 1)
Diseases named in the same sentence as CXCL1 in open-access papers (continued):
Sharing a sentence is not in itself a finding about the gene and the disease.
breast carcinoma (continued). "More importantly, BHS, a highly effective natural product with low toxicity, was presented as a promising chemosensitiser to inhibit breast cancer chemoresistance and metastasis by suppressing EV‐Apo/CXCL1 biogenesis and secretion." (PMID 39051750, 2024). "Professor Xu and his colleagues, for instance, used scRNA sequencing to identify a tumor cell subset with high expression of CXCL1, which was confirmed to promote LN metastasis in breast cancer." (PMID 38755647, 2024). "It was also observed that CXCL1 knockdown in TAMs enhanced chemosensitivity of breast cancer to paclitaxel, and treatment with the autophagy inhibitor 3-Ma increased the chemosensitivity of paclitaxel when administered in conjunction with TAMs." (PMID 39394189, 2024). "CXCL1 can promote breast cancer growth and metastasis through multiple mechanisms, such as inducing epithelial-mesenchymal transformation, promoting the self-renewal of CSCs, inducing autophagy, and accelerating MDSC infiltration and PMN formation." (PMID 38654356, 2024). "BHS effectively inhibits breast cancer metastasis and the activation of TAMs/CXCL1 in mouse breast cancer xenografts as well as in a zebrafish model of breast cancer xenotransplantation." (PMID 39257397, 2024). "TAMs-secreted CXCL1 mediates the EMT in breast cancer cells and induces the NF-κB-mediated expression of several metastatic genes, such as SRY-box transcription factor 4 (SOX4)." (PMID 38397187, 2024). "Subsequently, cell growth was examined on breast cancer cells in the presence of CXCL1 cytokine or its neutralizing antibody to determine their response to several chemotherapy drugs." (PMID 39394189, 2024). "For the in vivo study, Balb/c-nu-nu mice were utilized to establish breast cancer xenografts to investigate the impact of TAMs/CXCL1 on chemoresistance and autophagic process." (PMID 39394189, 2024). "The levels of CXCL1 are significantly higher in metastatic lung cancer specimens compared to primary breast cancer tumor, suggesting the active role of CXCL1 in the promotion of breast cancer cell migration and invasiveness." (PMID 38397187, 2024). "The investigation focused on the impact of CXCL1 on chemoresistance in breast cancer, given its high abundance as a chemokine secreted by TAMs in metastatic breast cancer." (PMID 39394189, 2024). "The chemokine profiling of murine and human breast cancer models indicated that CXCL1 is one of the most abundant chemokines secreted by TAMs." (PMID 38397187, 2024). "Our previous study has revealed the important role of TAM-derived CXCL1 in promoting breast cancer metastasis and validated its therapeutic value." (PMID 38654356, 2024). "It has been reported that CXCL1 expression is significantly correlated with metastasis and poor OS in patients with breast cancer." (PMID 38654356, 2024). "The data from this study showed that high serum levels of TNFα and Groα/CXCL1 increased OR for breast cancer at age ≤ 50 and age > 50 years in both AA and LA women." (PMID 38541912, 2024). "Curcumin inhibits breast cancer cell metastasis by reducing the expression of chemotactic cytokines CXCL1 and -2 whose messenger RNA level rely on NF-κB and needs complete IκBα expression." (PMID 37191432, 2023). "LIF expression in these cells is increased as a result of signal transducer and activator of transcription 3 (STAT3) activation by CXCL1 from breast cancer cells." (PMID 37108425, 2023). "We compared the values of the Cxcl1-to-S100a8 ratio in patients with grade 1, 2, or 3 breast cancers." (PMID 37553342, 2023). "On the contrary, data from about 3000 patients from The Cancer Genome Atlas (TCGA) database showed overexpression of CXCL1 mRNA in only 4–7% of breast cancer (BC) patients." (PMID 37370728, 2023). "In breast cancer, osteocytes can promote the proliferation and migration of breast cancer cells through the potential CXCL1/2 mechanism." (PMID 37206921, 2023).
breast carcinoma (continued). "An increase in CXCL1 levels in breast cancer correlates with larger tumors, higher-grade malignancies, and shorter survival times for breast cancer patients." (PMID 37210553, 2023). "The circulating levels of CXCL1 are the highest in patients with lung metastasis in breast cancer and higher than in patients with bone metastasis." (PMID 37108425, 2023). "All these results indicate that TAM/CXCL1 signaling plays a crucial role in mediating CUMS-induced breast cancer progression." (PMID 37210553, 2023). "For instance, CXCL12, CCL2, CCL5, and CXCL1 have been shown to regulate growth and stimulate the proliferation of melanoma, glioma, prostate cancer cells, and breast cancer cells." (PMID 37762405, 2023). "In contrast, CXCL1 expression is the highest in basal-like breast cancer and higher than in normal tissue." (PMID 37108425, 2023). "At the same time, CXCL8/IL-8 appears to be more important in the formation of bone metastasis of breast cancer than CXCL1." (PMID 37108425, 2023). "In mice with EO771 breast cancer, the abundances of CXCL1 in the diseased lungs of Ifng−/− mice and Il17a/Il17f−/− mice were 6% and 18% of that in the diseased lungs of mock C57 mice." (PMID 37553342, 2023). "For instance, breast cancer cells overexpress CXCL1/2 to attract myeloid cells into tumors, which in turn generate S100A8/A9 to confer chemoresistance properties to cancer cells and support their survival." (PMID 38093319, 2023). "In murine breast cancer xenografts, neutrophil infiltration within the tumor microenvironment was recruited by CXCL1 secreted by mesenchymal stromal cells (MSCs), subsequently resulting in metastasis." (PMID 37210553, 2023). "CXCL1 also induces the EMT of breast cancer cells, as shown by experiments on MDA-MB-231, HCC-1937, SKBR3, and MCF-7 cell lines." (PMID 37108425, 2023). "It was shown that CXCL1 promoted the survival of breast cancer cells by recruiting myeloid cells in tumors which produce paracrine cytokines to promote tumor survival and metastasis." (PMID 36614235, 2023). "CXCR2 expression is also reduced in ER-negative and HER2-negative breast cancers, indicating a decrease in CXCL1 activity in these tumors and in tumor cells that have lost the expression of these receptors." (PMID 37108425, 2023). "CXCL1 has also been found to have a significant effect on the formation of metastasis of breast cancer cells to various organs." (PMID 37108425, 2023). "In a combined cohort of breast cancer patients, c-Met expression is positively correlated to G-CSF, GM-CSF, CXCL1, and CXCL2." (PMID 37174093, 2023). "Curcumin also down-regulated the pro-inflammatory cytokine CXCL1 and -2 in cells separated from some essential human breast cancers, which are possible targets of miR181b." (PMID 37191432, 2023). "CXCL1 exerts its anti-apoptotic effect by affecting the expression of Bcl-2 family proteins, which inhibits breast cancer cell apoptosis induced by anticancer therapy." (PMID 37108425, 2023). "CXCL1 can also indirectly induce the EMT of breast cancer cells through recruiting MDSC, which then causes the EMT of breast cancer cells via IL-6." (PMID 37108425, 2023). "CXCL1 expression in breast cancer cells can also be altered by the plasminogen activation regulatory system." (PMID 37108425, 2023). "CXCL1 also causes the migration and epithelial-to-mesenchymal transition (EMT) of breast cancer cells, with the effect being lineage-dependent." (PMID 37108425, 2023). "CXCL1 expression is higher in breast cancer metastasis (a group composed mainly of liver, lung, skin, and other metastases) than in primary tumors and higher than in normal tissue." (PMID 37108425, 2023). "CXCL1 induces breast cancer cell migration through the activation of extracellular signal-regulated kinase (ERK) MAPK, which increases the expression of matrix metalloproteinase 2 (MMP2) and matrix metalloproteinase 9 (MMP9)." (PMID 37108425, 2023).
breast carcinoma (continued). "Here we show that an increased production of key cytokines (IL‐6, IL‐8, MCP‐1 and CXCL1), known to facilitate transmigration of breast cancer cells across the BBB, were increased following NHA exposure to MBM‐EVs or miR‐146a‐5p mimic." (PMID 37759347, 2023). "The following in vivo study further demonstrated that TAM co-injection with 4T1 cells significantly promoted breast cancer growth and metastasis, while CXCL1 silencing in TAMs remarkably inhibited the process." (PMID 37210553, 2023). "Inhibition of breast cancer metastasis via the suppression of NFjB activation and the expression of two prometastatic cytokines, CXCL1 and -2." (PMID 37191432, 2023). "Our study not only demonstrates a novel molecular mechanism of PMN formation, but also provides clinical insights into the therapeutic implication of ACACA and CXCL1 to prevent lung metastasis in breast cancer." (PMID 36607556, 2023). "CXCL1 expression in stroma breast cancer is also higher in invasive ductal carcinoma than in ductal carcinoma in situ, which indicates that CXCL1 expression increases with tumor growth." (PMID 37108425, 2023). "The highest production of CXCL1 of all breast cancer lines occurs in triple-negative MDA-MB-231 breast cancer cells (ER−PR−HER2−)." (PMID 37108425, 2023). "A bioinformatics study indicated that CXCL1 is an important gene in breast cancer processes in young adults." (PMID 37108425, 2023). "Contrary to these studies, conditioned media from mechanically stimulated MLO-Y4 osteocyte-like cells increased breast cancer cell growth by producing CXCL1 and CXCL2." (PMID 37174109, 2023). "CXCL1 plays a significant role in the development and progression of breast cancer, cervical cancer, endometrial cancer, ovarian cancer, and prostate cancer." (PMID 37108425, 2023). "CXCL1 expression is the lowest in luminal breast cancer and at the same time lower than in normal tissue." (PMID 37108425, 2023). "Consistently, in the present study, we verified that the N1-to-N2 chemoattractant ratio, such as the Cxcl1-to-S100a8 ratio, in the synthetic and endogenous MNs correlated with the aggressiveness of breast cancer and the disease progression." (PMID 37553342, 2023). "CXCL1-induced migration can be either directly via the activation of the CXCR2 receptor on breast cancer cells or indirectly." (PMID 37108425, 2023). "In the present study, we investigated the plasma concentrations of CXCL1 and CXCL8 in female breast cancer patients as potential tumor markers in the diagnostic process, as an individual or combined parameter with the routinely used marker CA 15-3." (PMID 36431173, 2022). "In basal-like and BRCA1-related breast cancers, ROS expression was correlated with AhR levels and the expression of the chemokines CXCL1, CXCL2, and CCL5." (PMID 36588678, 2022). "Increased TADC-derived CXCL1/GRO and S100A8/A9 were associated with DOX/cyclophosphamide resistance in breast cancer." (PMID 36359776, 2022). "CXCL1 generally promotes tumor progression in melanoma, colorectal cancer, breast cancer and other tumors." (PMID 35754838, 2022). "The data showed that brain metastatic breast cancers expressed significantly increased (p = 0.0058) levels of CXCL1." (PMID 35158784, 2022). "Our findings are clinically relevant, as VEGF, CXCL1, and CXCL16 mRNA expression is associated with OSM and/or OSMR levels in breast cancer patients and with decreased overall survival." (PMID 35192545, 2022). "In breast cancer, CXCL1 can elicit cancer progression and immune escape programs, and targeting the CXCL1/CXCR2 axis can improve treatment." (PMID 35468838, 2022). "Senescent mammary fibroblasts stimulate the proliferation of breast cancer cells by secreting IL-6, IL-8, and C-X-C motif chemokine ligand 1 (CXCL1)." (PMID 36291773, 2022).
breast carcinoma (continued). "CXCL1 is expressed in breast cancer cells and the stroma surrounding the cancerous lesion, and the expression levels of this chemokine depended on the size and stage of the tumor and the abundance of metastases." (PMID 36431173, 2022). "In vitro, CXCL1 stimulated the proliferation, invasion, and migration of breast cancer cells while inhibiting apoptosis, which seems to partially explain the unfavorable prognosis of patients with overexpression of this chemokine." (PMID 36431173, 2022). "CXCL1 is significantly correlated with T lymphocyte infiltration, during the progression of breast cancer CXCL1 is up‐regulated by Th17 cells and can promote the growth and development of breast cancer." (PMID 33626234, 2021). "XP impaired the activation of hematopoietic stem-progenitor cells (HSPCs) as well as the differentiation of HSPCs into MDSCs through TAMs/CXCL1 signaling pathway to inhibit lung metastasis of breast cancer." (PMID 34722304, 2021). "TAM/CXCL1 inhibition represents a promising treatment strategy for preventing breast cancer immune escape and lung metastasis." (PMID 34461944, 2021). "The results showed that the expression of CXCL1 was near related to superior OS in breast cancer patients." (PMID 33959656, 2021). "In this breast cancer subtype, cancer stem cells (CSCs) expressed increased amounts of CXCL1, which sustained CSC proliferation and self-renewal." (PMID 34503058, 2021). "The survival curve suggested that OS was significantly shortened in breast cancer patients with low expression of CXCL1." (PMID 33959656, 2021). "CXCL1 was significantly expressed at high levels in 21 unique analyses in colon cancer and significantly expressed at low levels in 15 unique analyses in breast cancer." (PMID 34439306, 2021). "Previous data from our laboratory demonstrate that DIO mice with mammary carcinoma display reduced immunotherapeutic efficacy, in part due to CXCL1-driven accumulation of FASL+ MDSCs inducing apoptosis in effector CD8+ TILs." (PMID 34064933, 2021). "This study reveals the immunomodulatory mechanism of ADQ in inhibiting breast cancer metastasis and highlights the TAM/CXCL1/Treg axis as a promising therapeutic target for breast cancer immunotherapy." (PMID 34461944, 2021). "In this study, by using the in vitro co-culture system and the in vivo co-injection methods, TAM/CXCL1 within the TME was identified as the pivotal target of ADQ in inhibiting breast cancer immune escape and lung metastasis." (PMID 34461944, 2021). "TAMs remain one of the most abundant immune cell subpopulations in breast cancer, and CXCL1 is among the most abundant chemokines secreted by TAMs." (PMID 34461944, 2021). "Our previous studies have indicated that inhibiting the TAM/CXCL1 activity within the TME significantly suppressed breast cancer immune escape and metastasis." (PMID 34461944, 2021). "Herein, we systematically demonstrated that ADQ suppressed the immune escape and lung metastasis of breast cancer by remodeling the immunosuppressive TME via suppressing the TAM/CXCL1/Treg pathway." (PMID 34461944, 2021). "ADQ suppressed the immune escape and lung metastasis of breast cancer by remodeling the immunosuppressive TME via blocking the TAM/CXCL1/Treg pathway." (PMID 34461944, 2021). "Our recent report demonstrated that TAMs‐derived CXCL1 exerted an important role in recruiting breast cancer cells into the PMN." (PMID 33463063, 2021). "According to large-scale sequencing results, the level of CXCL1 in normal tissue is higher than that in breast cancer." (PMID 33959656, 2021). "It is found that CXCL1 can induce chemoresistance and metastasis of breast cancer via CXCR2 activation." (PMID 33463063, 2021). "CXCL1 is among the most abundant chemokines secreted from TAMs, and its level in mammary tumor tissue is significantly elevated compared with that in normal breast tissue." (PMID 34461944, 2021).
breast carcinoma (continued). "More importantly, ADQ treatment also significantly delayed TAM co-injection-induced mammary tumor growth, while CXCL1 overexpression in the co-injected TAMs partially abrogated that effect." (PMID 34461944, 2021). "Meanwhile, other chemokines, such as CXCL1, have also been demonstrated to enhance breast cancer migration, invasion, and EMT by upregulating the NF-KB/SOX4 signaling pathway." (PMID 32283687, 2020). "Significantly, the present study highlights one of the first potential upstream candidates in breast cancer in the form of the visfatin-monocyte-CXCL1 pathway." (PMID 33256011, 2020). "Recent studies indicate that CXCL1 is highly expressed in bladder cancer, breast cancer, and prostate cancer." (PMID 33489879, 2020). "The transcriptional levels of CXCL9/10/11/13 in breast cancer tissues were significantly elevated while the transcriptional levels of CXCL1/2/3/12 were decreased based on intersections of Oncomine database and GEPIA." (PMID 32963527, 2020). "CXCL10 plays indispensable role in breast cancer patients for immune checkpoint-based therapies, while CXCL1 had been shown to be involved in resistance to cancer chemotherapies." (PMID 32963527, 2020). "We noted that recombinant CXCL1 increased invasion and migration in breast cancer cell lines, with CXCL1 blocking antibody abolishing the enhancement of malignant behavior by V-THP-1 CM." (PMID 33256011, 2020). "As the CXCL1/CXCR2 axis is required for lung metastasis in breast cancer, we therefore analyzed levels of CXCL1/CXCR2 expression in lung specimens." (PMID 32079335, 2020). "In breast tumor tissues from n=88 patients with basal breast cancer, CXCL1 and FASLG expression were found to increase significantly as the MDSC expression score increased." (PMID 33123173, 2020). "In summary, this study demonstrated that visfatin enhanced breast cancer progression via pERK/CXCL1 induction in macrophages." (PMID 33256011, 2020). "The results indicated that the expression levels of CXCL9, CXCL10, CXCL11, and CXCL13 were marked higher in breast cancer tissues than in normal tissues, while the expression levels of CXCL1, CXCL2, CXCL3, and CXCL12 were lower inversely." (PMID 32963527, 2020). "Oncomine database revealed that mRNA expressions of CXCL9/10/11 were significantly higher in human breast cancer than in normal tissues in multiple datasets and transcription levels of CXCL1/2/4/5/7 were prominently low." (PMID 32963527, 2020). "To more precisely examine the effect of macrophages on breast tumors, we selected immune cells within breast cancer tissue for CXCL1 and pERK IHC signal analysis." (PMID 33256011, 2020). "For example, breast cancer-derived CXCL1/2 is able to attract CD11b+Gr1+ myeloid cells, and this then promotes cell survival and metastasis." (PMID 32415115, 2020). "Along these lines, CXCL1 as well as CXCL8 have been found to promote the proliferation of breast cancer cells." (PMID 32582148, 2020). "In different types of cancers (including breast cancer and melanoma), CXCL1, CXCL2, and CXCL5 with their common receptor CXCR2 trigger the recruitment of MDSCs into the PMN." (PMID 33123472, 2020). "Taken together, CXCL1 plays a vital role in breast cancer cell progression and metastasis under the influence of visfatin-treated tumor-associated macrophages." (PMID 33256011, 2020). "In previous studies, CXCL1 has been reported to correlate with ERK phosphorylation in breast cancer, colorectal cancer, and LPS-induced inflammation." (PMID 33256011, 2020). "Visfatin promoted M2 differentiation in monocytic cells through ERK/CXCL1 induction and enhanced breast cancer cell viability, migration, tumorsphere formation, EMT, and stemness." (PMID 33256011, 2020). "We report that obesity increases CXCL1 concentrations in the mammary tumor microenvironment, driving CXCR2-mediated chemotaxis and accumulation of granulocytic myeloid-derived suppressor cells (G-MDSCs) expressing Fas ligand (FasL)." (PMID 33123173, 2020).